SMAD3 (SMAD family member 3)
Diseases named in the same sentence as SMAD3 in open-access papers (continued):
Sharing a sentence is not in itself a finding about the gene and the disease.
Crohn disease (12 papers, 2007 to 2024). A gastrointestinal disorder characterized by chronic inflammation involving all layers of the intestinal wall, noncaseating granulomas affecting the intestinal wall and regional lymph nodes, and transmural fibrosis. "Even among Western patients, SMAD3 rs17293632 is a susceptibility locus in Crohn’s disease." (PMID 33036415, 2020). "Specific examples of fine-mapped signals include a Crohn's disease risk variant located in the intron of SMAD3 (rs17293632, C>T) that prevents the robust binding of AP-1, which in turn disrupts AP-1 regulation of TGF-β–SMAD3 pathway and highlights a potential mode of action to increase disease risk." (PMID 26157023, 2015). "Therefore, herbs-partitioned moxibustion combined with acupuncture can prevent intestinal epithelial mesenchymal transition by inhibiting abnormal expression of TGFβ1, TβR2, Smad3, and Snail in the TGF-β1-Smad-Snail pathway in Crohn's disease." (PMID 31275422, 2019). "The high SMAD7 immunoreactivity and lack of p-SMAD3 expression in the LP suggests defective TGF-β signaling in the LP in EE similar to a previously reported SMAD7-mediated inflammatory pathway in refractory CD and Crohn’s disease." (PMID 29415065, 2018).
inflammatory bowel disease (12 papers, 2012 to 2025). A spectrum of small and large bowel inflammatory diseases of unknown etiology. "Single-nucleotide polymorphisms (SNPs), such as rs36221701, which are located upstream of SMAD3, are significantly related to gene expression in inflammatory bowel disease (IBD), which may increase CRC risk by 3- to 5-fold." (PMID 33036415, 2020). "The reason for the inflammatory signaling pathways predominant in MG is probably because the inflammatory bowel disease (IBD) risk genes (e.g., SMAD3 and OSMR) were significantly expressed in MG." (PMID 36693960, 2023). "In humans, genome wide association studies (GWAS) have linked the SMAD3 locus - a key component of the TGF-β pathway - to predisposition to inflammatory bowel disease (IBD) and asthma." (PMID 36569843, 2022). "Meeker and colleagues showed that increased concentrations of vitamin D in Smad3 knockout mice was beneficial in preventing inflammation-associated bacterially driven colon cancer and inflammatory bowel disease (IBD)." (PMID 34820334, 2021). "Silencing SMAD7 can restore TGFβ/SMAD3 signaling and result in the suppression of inflammatory cytokine production in patients with inflammatory bowel diseases." (PMID 26446848, 2015). "Inhibiting Smad7 can restore the TGF-β1/Smad3 signaling and result in the suppression of inflammatory cytokine production in patients with inflammatory bowel diseases." (PMID 22429929, 2012). "The inflammatory bowel disease is highlighted (q-value = 0.015) through KEGG enrichment analysis using FABIO significant genes, and the involved genes are IL18RAP, IL4, GATA3, and SMAD3 (FABIO PIP = 1, 0.76, 1, and 0.75, respectively)." (PMID 39621803, 2024). "Interestingly, in inflammatory bowel disease, silencing of SMAD7 with anti-sense oligonucleotide treatment restored SMAD3 activation and reduced synthesis of inflammatory cytokines by endogenous TGFβ." (PMID 27473228, 2016). "MNV-4 infection was observed to accelerate the progression of bacteria-induced inflammatory bowel disease in the multidrug resistance gene mdr1a knockout mice but it did not modulate the progression of inflammatory bowel disease in the Smad3 knockout mice." (PMID 24847970, 2014).
Nephropathy (12 papers, 2015 to 2023). A nonspecific term referring to disease or damage of the kidneys. "Among TGF-β/Smad signaling, Smad3 is pathogenic because genetic deletion or pharmacological inhibition of Smad3 can protect against Ang II-induced hypertensive cardiopathy and nephropathy." (PMID 37449045, 2023). "Previous studies for microRNA-451 revealed an early increase in its level in the tissue of the kidney and later on a decrease in urine, reflecting the increased activity of signal pathways such as MAPK9 and SMAD3 in association with the process of nephropathy development." (PMID 32855824, 2020). "It has been well established that Ang II induces hypertensive cardiopathy and nephropathy by activating TGF-β/Smad3 signaling directly and indirectly via the TGF-β and ERK/p38 MAPK-Smad crosstalk pathways." (PMID 37449045, 2023). "We first examined TGF‐β1 expression in ADR‐induced FSGS and found that a massive Smad3 activation (phosphorylation) was evidenced in the glomeruli of ADR‐induced nephropathy, which was blocked by podocyte‐specific Btg2 knockout." (PMID 37749872, 2023). "Thus, targeting Smad3 via genetic deletion or pharmacological inhibition of Smad3 can inhibit hypertensive cardiopathy and nephropathy." (PMID 37449045, 2023).
pulmonary hypertension (12 papers, 2016 to 2024). Increased pressure within the pulmonary circulation due to lung or heart disorder. "Finally, SMAD3, an intracellular signal transducer and transcriptional modulator, has been implicated in pulmonary arterial hypertension through vascular remodeling, cardiac fibrosis and renal inflammation and fibrosis." (PMID 38326862, 2024). "Previous study demonstrated that BMPR-II affected the SMAD3 expression in pulmonary arterial hypertension." (PMID 36008606, 2022). "PPARγ directly binding to Smad3 plays a protective role, which has been reported in pulmonary arterial hypertension (PAH)." (PMID 36275905, 2022). "Beraprost sodium is now being used for the treatment of pulmonary hypertension that acts by inhibiting overactive TGFβ signaling by reducing SMAD3 and p38MAPK24." (PMID 28874783, 2017). "Nevertheless, pulmonary hypertension has not been described among patients with SMAD3 or SMAD4 mutations." (PMID 32260370, 2020). "We presented new data showing that crocin attenuates pulmonary hypertension, pulmonary vascular remodeling, and RV hypertrophy in HPH mice, likely through blockade of hypoxia-induced hyperactivity of TGF-β1/Smad3 signaling and inhibition of fibroblast activation." (PMID 38830933, 2024). "Upregulation of miR-199a-5p has been reported in the lung tissue from mouse and rat models of pulmonary artery hypertension (PAH), which also identified SMAD3 (which plays a key role in transmitting TGF-β signals from cell surface receptors to the nucleus) as a target gene of miR-199a-5p." (PMID 36200021, 2022).
autoimmune disease (11 papers, 2015 to 2024). A disorder resulting from loss of function or tissue destruction of an organ or multiple organs, arising from humoral or cellular immune responses of the individual to their own tissue constituents. "Although Smad3 has been considered to be a key transcription factor activated in response to many fibrogenic mediators, knockout of Smad3 can cause autoimmune disease." (PMID 33390954, 2020). "The tight interaction with the IRF1/survivin or survivin/SMAD3 complexes maintains expression of IFN-sensitive genes that are clinically relevant in several autoimmune diseases, including RA,48,64 systemic lupus erythematosus, and Sjögren’s syndrome." (PMID 36425763, 2022). "An AP-1 site in an intron of the SMAD3 gene has been implicated in the association of this gene with CAD, as well as an autoimmune disease." (PMID 31014396, 2019). "An AP-1 cognate binding site in an intron of the SMAD3 gene has been shown to regulate expression of this gene and implicated as causal for both CAD and autoimmune diseases." (PMID 31014396, 2019). "By revealing the opposite regulatory functions of Ash1l and lnc-Smad3 in Smad3 expression, our data provide insights for the epigenetic control of Treg cell fate to potentially aid in the development of therapeutic intervention for autoimmune diseases." (PMID 28598443, 2017).
COVID-19 (11 papers, 2021 to 2023). A disease caused by infection with severe acute respiratory syndrome coronavirus 2. "Thus, it is highly possible that TGF-β/Smad3 signaling may contribute to COVID-19-associated AKI, which is warranted for further investigation." (PMID 33907513, 2021). "In contrast, many TFs were identified specifically as the top TFs in COVID-19 patients’ lung cell types, including SMAD3 in ciliated cells, NFKB1 and JUN in dendritic cells, PPARG in macrophage/monocyte cells, and STAT3 in T cells." (PMID 35458567, 2022). "Regarding the TRN of COVID-19 patients’ ciliated cells, its top TF SMAD3 was only identified to be targeted by SIS3." (PMID 35458567, 2022). "We therefore measured SMAD3 in left ventricular tissue from deceased COVID-19 patients and found the mRNA levels to be significantly increased." (PMID 34745111, 2021). "As SARS-CoV-2 N protein can enhance TGF-β/Smad3 signaling to cause tubular epithelial cell death and AKI via the G1 cell cycle arrest mechanism, the regulation of TGFB1 might be significant in COVID-19 AKI." (PMID 37274117, 2023). "Moreover, both deletion of Smad3 and treatment with SIS3, the inhibitor of Smad3, can restore the SARS-CoV-2 N-induced AKI, which indicated that targeting Smad3 may represent a novel therapy for COVID-19-associated AKI." (PMID 35655782, 2022). "Thus, targeting Smad3 may represent as a novel and promising therapeutic strategy for critically ill COVID-19 patients." (PMID 35541902, 2022). "Since TGF-β and Activin A both induce SMAD3 phosphorylation and similar downstream signaling, the relative importance of Activin A– vs TGF-β–induced cardiac dysfunction in patients with COVID-19 requires further elucidation." (PMID 36440002, 2022). "From 11 healthy cell-type TRNs and 8 COVID-19 cell-type TRNs, we identified 8 unique central TFs, FOXP1, RUNX1, FOS, SMAD3, JUN, NFKB1, PPARG, and STAT3." (PMID 35458567, 2022).
Stroke (11 papers, 2013 to 2025). Sudden impairment of blood flow to a part of the brain due to occlusion or rupture of an artery to the brain. "The TGF‐β/Smad3 signaling pathway is implicated in numerous pathological processes associated with brain disorders, including stroke, traumatic brain injury, and Parkinson's disease." (PMID 40831324, 2025). "Moreover, we found that EA treatment downregulated microglial polarization‐associated neuroinflammation by regulating the TGF‐β/Smad‐3 signaling pathway, highlighting a potential therapeutic mechanism of EA in stroke recovery." (PMID 40831324, 2025). "In short, circUSP36 inhibits astrocyte apoptosis and reduces neuronal damage after stroke through the miR-139–3p/SMAD3/Bcl-2 axis." (PMID 38203348, 2023). "GDF11 promotes the expression of Smad3, which inhibits cell apoptosis and reduces brain injury after stroke by activating the TGF-β/Smad3 signaling pathway." (PMID 38203348, 2023). "Histologic analysis revealed higher phospho-SMAD3 immunoreactivity in RbpjiPC than in control stroke samples, an effect that partially resembles the phenotype seen in postnatal mutants." (PMID 31249304, 2019). "CircUSP36 attenuates stroke-induced brain injury through the miR-139-3p/SMAD3/Bcl2 signaling axis and circUSP36 could be a potential therapeutic target for IS." (PMID 38682035, 2024). "The expression of EndoMT marker p-SMAD3 increased in ECs until RP8D and decreased at RP34D after stroke." (PMID 40667795, 2025). "CircUCK2 can activate the TGF-β/Smad3 signaling pathway through the miR-125b-5p/GDF11 axis in order to reduce cell apoptosis and improve neuronal injury after stroke." (PMID 38203348, 2023). "Results showed that the expression of VDR, TGF-β, p-Smad2/Smad2, p-Smad3/Smad3, and VEGF in the periinfarcted cortex was significantly higher than DMSO group 3 days after stroke." (PMID 35369317, 2022).
systemic sclerosis (11 papers, 2014 to 2024). A chronic disorder, possibly autoimmune, marked by excessive production of collagen which results in hardening and thickening of body tissues. "Then, phosphorylation of Smad3 was constitutively increased in systemic sclerosis derived fibroblasts, and Smad3-deficient mice represented the decrease of collagen deposition compared to wild-type mice when given the treatment of kidney injury." (PMID 33789737, 2021). "Consistent with our observations in OC metastasis, TGF-β1 has also been reported to upregulate TRIB3 expression in an SMAD3-dependent manner in fibroblasts in systemic sclerosis and murine alveolar type II epithelial cells." (PMID 39719444, 2024). "Some studies have demonstrated a constitutive increased SMAD3 phosphorylation in systemic sclerosis fibroblasts." (PMID 37435075, 2023). "A similar mechanism was described in the context of systemic sclerosis wherein primary human skin fibroblasts treated with the VDR agonist paricalcitol, ligand-bound VDR associated with phosphorylated SMAD3 to inhibit downstream gene transcription." (PMID 26061181, 2015). "Administration of Astragalus polysaccharide in bleomycin-induced systemic sclerosis mice reduced the collagen production in skin tissue, also downregulating the TGF-β1, MCP-1, Smad2, and Smad3 mRNA expressions." (PMID 34258301, 2021). "The expression of JMJD3 was found increased in fibroblasts in systemic sclerosis (SSc) skin and in experimental fibrosis in a TGF-β/SMAD3 signaling dependent manner." (PMID 31701394, 2019). "In addition, transforming growth factor‐β (TGF‐β), a key factor in organ fibrosis, increases interleukin‐13 synthesis by GATA3 in T‐lymphocytes from patients with systemic sclerosis 33 and GATA3 could physically and functional interact with Smad3, a component of TGF‐β signalling pathway." (PMID 27709831, 2017).
chordoma (10 papers, 2018 to 2024). Chordomas are rare malignant tumors arising from embryonic remnants of the notochord in axial skeleton. "Smad3 expression was inhibited by the mimics but promoted by the inhibitors, confirming that miR-16-5p interacts with Smad3 to suppress chordoma cell malignancy." (PMID 36792585, 2023). "What’s more, the expression of Smad3 and circTLK1 decreased in chordoma cells after transfecting with si-Smad3#1 and si-Smad3#2." (PMID 36792585, 2023). "miR-16-5p expression was reduced in chordoma and it suppresses cancer cell proliferation and invasion via targeting Smad3." (PMID 36760720, 2023). "further revealed that circTLK1 can regulate the biological functions of miR-16-5p through sponge adsorption, thus forming a circTLK1/miR-16-5p/Smad3 positive feedback loop to promote chordoma invasion, migration, and epithelial–mesenchymal transition." (PMID 37720221, 2023). "Previously, we found that miR-16-5p inhibited chordoma growth and progression via suppressing Smad3 expression." (PMID 36792585, 2023). "For example, miR-16–5p is reported to be down-regulated in chordoma and it can suppress chordoma cell proliferation, invasion and metastasis by targeting Smad3." (PMID 34721048, 2021). "miR-16-5p is known to inhibit the growth and metastasis of chordoma by targeting the expression of Smad3." (PMID 32982740, 2020). "Then, using a luciferase reporter assay, we confirmed that Smad3 was a direct target of miR-16-5p in chordoma cells and that miR-16-5p directly regulated Smad3 expression at the posttranscriptional level." (PMID 29880900, 2018). "Taken together, our results demonstrate that Smad3 is a direct target of miR-16-5p in chordoma cells and that miR-16-5p directly regulates Smad3 expression at the posttranscriptional level." (PMID 29880900, 2018). "To further investigate the role of Smad3 in chordoma cells, we transfected Smad3 siRNA into U-CH1 and U-CH2 cells and then confirmed the downregulation of Smad3 by qRT-PCR and western blotting." (PMID 29880900, 2018). "Further research showed that knockdown of Smad3 had an effect similar to that of overexpression of miR-16-5p in chordoma cells." (PMID 29880900, 2018). "Our results show that knockdown of Smad3 had an effect similar to that of overexpression of miR-16-5p in chordoma cells." (PMID 29880900, 2018). "To identify the expression of Smad3 in chordoma tissues, we performed IHC in 54 paraffin-embedded pathological chordoma specimens and found that Smad3 was highly expressed in chordoma tissues." (PMID 29880900, 2018). "Our results showed that the expression of Smad3 was upregulated in chordoma compared with that in muscle." (PMID 29880900, 2018). "Then, we performed a luciferase reporter assay to confirm that miR-16-5p directly binds to the 3′-UTR of Smad3 in chordoma cells." (PMID 29880900, 2018). "However, in the present study, we explored the novel mechanism through which circTLK1 promotes chordoma progression by regulating a positive feedback pathway involving miR-16-5p/Smad3." (PMID 36792585, 2023). "In addition, circTLK1 directly interacted with miR-16-5p, which has previously been shown to repress chordoma, and circTLK1 knockdown suppressed Smad3 expression." (PMID 36792585, 2023). "MiR-16-5p can inhibit the proliferation, invasion and metastasis of chordoma by targeting SMAD3." (PMID 32774166, 2020). "Furthermore, Smad3 was identified as a target of miR-16-5p and was highly expressed in chordoma tissues." (PMID 29880900, 2018). "Our findings demonstrated a tumor suppressor role of miR-16-5p in chordoma progression by targeting Smad3, which provides new insight into the molecular mechanism of chordoma and may offer a possible therapeutic strategy for chordoma treatment." (PMID 29880900, 2018). "Our findings demonstrate that miR-16-5p plays a tumor suppressor role in chordoma progression by targeting Smad3, which could provide a promising prognostic and therapeutic strategy for chordoma treatment." (PMID 29880900, 2018).
chordoma (continued). "Taken together, our findings demonstrate a tumor suppressor role of miR-16-5p in chordoma progression by targeting Smad3, which could provide a promising prognostic and therapeutic strategy for chordoma treatment." (PMID 29880900, 2018). "Furthermore, Smad3 was identified as a target of miR-16-5p, and Smad3 was highly expressed in chordoma tissues." (PMID 29880900, 2018). "The expression of Smad3 was significantly downregulated in miR-16-5p overexpressing chordoma cells." (PMID 29880900, 2018). "Furthermore, Smad3 was highly expressed in chordoma tissues and it was correlated with surrounding invasion, and further research showed that knockdown of Smad3 had the same effect as overexpression of miR-16-5p in chordoma cells." (PMID 29880900, 2018). "Knockdown of Smad3 suppressed the migration and invasion of chordoma cells and was accompanied by the upregulation of E-cadherin and downregulation of N-cadherin and vimentin, which indicated that Smad3 may be involved in the metastasis of late-stage chordoma by promoting EMT." (PMID 29880900, 2018).
hypertensive nephropathy (10 papers, 2013 to 2024). Kidney damage that results from chronically elevated blood pressure; complications include glomerular damage resulting in proteinuria and hematuria. "In rats with hypertensive chronic kidney disease, colchicine inhibited upregulation of fibronectin and type I collagen, and prevented SMAD3 phosphorylation, a canonical downstream mediator of TGF-β signaling." (PMID 36643998, 2021). "Thus, down-regulation of miR-29 in ANG II-mediated hypertensive nephropathy may be attributed to activation of both TGF-β/Smad3 and NF-κB pathways." (PMID 23301086, 2013).